ACE (angiotensin I converting enzyme)
Diseases named in the same sentence as ACE in open-access papers (continued):
Sharing a sentence is not in itself a finding about the gene and the disease.
Hypertension (continued). "Some already known bioactive peptides derived from marine resources have potential ACE inhibitory activity and can be considered therapeutic agents to treat hypertension." (PMID 33171852, 2020). "Food products that inhibit ACE activity in vitro have been considered ideal candidates for alleviation of hypertension." (PMID 32571292, 2020). "Studies involving various experimental models of hypertension have shown that the acute antihypertensive effect of ACE inhibitors is attenuated by blocking kinins with either high titer kinin antibodies or a B2 receptor antagonist." (PMID 33126450, 2020). "ACE inhibitors respectively ARBs are the preferred drugs for treating hypertension in patients with T2DM because of their nephroprotective potential." (PMID 32903568, 2020). "We also reported that a water-soluble extract obtained from this unfiltered VOO possesses ACE inhibitory activity and antihypertensive effect in an animal model of hypertension (spontaneously hypertensive rats, SHR)." (PMID 31968696, 2020). "ACE inhibitors or angiotensin receptor blockers, based upon strong evidence of efficacy, are commonly used in the management of hypertension, heart failure, post myocardial infarction care, and to slow progression of renal disease." (PMID 32624690, 2020). "Angiotensin-converting enzyme (ACE) inhibitors are a class of medications that have formed the backbone of hypertension management." (PMID 32782860, 2020). "The concomitantly related macrovascular complication of hypertension can be achieved by comparable extracts via the inhibition of the angiotensin I-converting enzyme (ACE)." (PMID 32707790, 2020). "Among other medicinal plants Hibiscus sabdariffa (roselle), is known to reduce BP using its ability to inhibit ACE, while Camellia sinensis (Tea) extracts can reduce hypertension by significantly increasing brachial artery flow-mediated dilation (FMD)." (PMID 32317975, 2020). "As far as we are concerned, hypertension resulted in worse deterioration of lung tissue, thus offsetting the originally increased serum ACE activity." (PMID 33238910, 2020). "Structures of the human ACE domains provided detailed insight into the mechanisms of substrate hydrolysis, and enabled the design of domain-selective ACE inhibitors for the specific treatment of hypertension (C-domain) and fibrosis (N-domain)." (PMID 33146371, 2020). "Following a high fiber, prebiotic, dietary supplement, there was a subsequent reduction in the use of medicine for diabetes (insulin) and hypertension treatment (ACE inhibitors), and also a lowering of blood pressure." (PMID 33072796, 2020). "ACE enzyme plays a significant role in blood pressure regulation and its inhibitors are widely used as a drug for the treatment of hypertension, myocardial infarction, heart failure, and diabetic nephropathy." (PMID 31980708, 2020). "According to the World Health Organization, hypertension complications are responsible for millions of deaths every year, and the use of ACE inhibitors has marked a great advancement in the treatment of hypertension." (PMID 32565815, 2020). "The inhibition of ACE function is also one of the widely used therapeutic options in the hypertension disease as this enzyme is involved in the renin-angiotensin axis of blood pressure regulation which is largely involved in the pathogenesis of hypertension." (PMID 33082415, 2020). "Several international heart associations recommend patients already using ACE inhibitors/ARBs and are infected with COVID-19 to continue using their medication (ACEI/ARB Use in COVID-19 Patients With Hypertension; Czarska-Thorley, 2020)." (PMID 33117174, 2020). "Hypertension or diabetes patients are always treated with ACE inhibitors and ARBs, which results in an upregulation of ACE2 expression." (PMID 32982925, 2020).
Hypertension (continued). "Angiotensin-converting enzyme (ACE) has a significant role in the regulation of blood pressure and ACE inhibition with inhibitory peptides is considered as a major target to prevent hypertension." (PMID 32012183, 2020). "Hypertension is one of the most common cardiovascular problems that origins/develops into other dangerous diseases in the world, where the angiotensin-converting enzyme (ACE) plays a major role in augmenting health risks." (PMID 32722220, 2020). "The drug most commonly used by patients in this study to treat hypertension was an angiotensin converting enzyme (ACE) inhibitor (1264 patients, 32.7%)." (PMID 33520303, 2020). "Angiotensin-converting enzyme (ACE) plays a prominent role in hypertension, heart failures, myocardial infarction, and diabetic nephropathy." (PMID 32256642, 2020). "It is well known that classical cascade in the RAS called the ACE/Ang II/Ang II type 1 receptor axis is a facilitating factor that promotes hypertension and damage to a variety of organs." (PMID 32458985, 2020). "Natural components with ACE inhibitory capacity have become a focus of hypertension treatment studies." (PMID 33317025, 2020). "Angiotensin-converting enzyme (ACE) inhibitors (ACEIs) and angiotensin II type‐1 receptor blockers (ARBs) are among the most widely prescribed drugs for the treatment of arterial hypertension, heart failure and chronic kidney disease." (PMID 32514935, 2020). "The one patient on metformin, pioglitazone, and vildagliptin reported prolonged fasting for 12 h in the 7-day diary, whereas the other patient on metformin, pioglitazone, and sitagliptin was also on ACE inhibitor therapy for hypertension." (PMID 32151247, 2020). "Natural ACE inhibitors, which can support hypertension treatment, represent various chemical groups, such as peptides, polyphenols, or carotenoids." (PMID 32630448, 2020). "T. violacea had the highest ACE inhibitor activity, demonstrating its potential in the treatment of hypertension." (PMID 32526850, 2020). "We identified other possible risk factors including overnight prolonged fasting (> 8 h), physical activity, alcohol consumption, and concomitant therapy (i.e., ACE inhibitors for hypertension)." (PMID 32151247, 2020). "In this sense, ACE inhibitors are bioactive substances with potential use as medicinal products for treatment or prevention of hypertension, heart failures, myocardial infarction, and other important diseases." (PMID 31940798, 2020). "Most of the 951 patients taking either ACE inhibitors or ARB at admission had hypertension, 87.9 and 90.3%, respectively, and beta-blocker use was reported for 29.9%, diuretic use for 24.3% and Ca-antagonist use for 22.8%." (PMID 33195473, 2020). "Serum ACE activity is always increased in patients with hypertension, as revealed by previous studies, which was different from our results." (PMID 33238910, 2020). "ACE inhibitors (ACE-Is) and angiotensin II receptor blockers (ARBs), two common therapies for hypertension, increase ACE2 levels in some tissues such as the myocardium, contributing to protection against cardiovascular disease (CVD)." (PMID 32575076, 2020). "All three participants treated with metformin only were also receiving ACE inhibitors for hypertension." (PMID 32151247, 2020). "The patient had poor control of hypertension, captopril, an angiotensin-converting enzyme (ACE) inhibitor, was added three weeks before presentation." (PMID 33312778, 2020). "Five of these patients were already on ACE-inhibitors or beta-blockers because of hypertension, and additional HF therapy was given." (PMID 33072403, 2020). "Recent studies on the antioxidant activity of food are complemented with the analysis of ACE inhibitory activity, since oxidative stress and hypertension have become the most serious health problems affecting society." (PMID 32093055, 2020).
Hypertension (continued). "ACE inhibitors have been shown to reverse LV hypertrophy in essential hypertension and in various experimental models of hypertension, in great part due to reduced afterload." (PMID 33126450, 2020). "Hypertension is usually treated with synthetic ACE inhibitors which can have adverse side effects, and therefore, a search for ACE inhibitors from natural sources is of increased concern." (PMID 32610526, 2020). "Angiotensin-converting enzyme (ACE) is implicated in the progression of kidney dysfunction and structural damages to chronic kidney diseases and associated hypertension." (PMID 32410988, 2020). "The findings showed that 20-HETE-induced hypertension in CYP4A2-transduced rats is associated with RAS upregulation and can be abrogated by ACE inhibition or angiotensin type 1 receptor (AT1R) blockade." (PMID 32549334, 2020). "While DPP4 inhibitors are effective against hyperglyceamia, for the treatment of hypertension ACE (angiotensin converting enzyme) inhibitors have been shown to be efficient and safe form of treatment." (PMID 33776749, 2020). "The PDA has recommended, since the year 2000, to all patients with diabetes, ACE inhibitors or angiotensin II receptor blockers in the case of hypertension or the presence of microalbuminuria." (PMID 33050012, 2020). "It should be noted that Captropril, i.e., the most common drug used in hypertension treatment, is also known as a competitive inhibitor of ACE." (PMID 32471271, 2020). "Based on available evidence we recommend that treatment with ACE inhibitors and ARBs should be continued in patients receiving it for hypertension management." (PMID 32923338, 2020). "The examined P4P incentives were intended to affect physicians’ choice between two hypertension drugs: angiotensin converting enzyme (ACE) inhibitors and angiotensin receptor blockers (ARB)." (PMID 31960248, 2020). "Enalapril is an angiotensin I-converting enzyme inhibitor used for the treatment of hypertension, mainly through the reduction of angiotensin II formation, but also through the increase of kinins half-life." (PMID 32528973, 2020). "Five patients with TS were treated for hypertension with β-blockers, angiotensin receptor blockers, or angiotensin converting enzyme (ACE) inhibitors." (PMID 33368097, 2020). "The major drug classes available for the management of hypertension are thiazide diuretics, angiotensin-converting enzyme (ACE) inhibitors, angiotensin receptor II blockers, and calcium channel blockers." (PMID 32317975, 2020). "Since oxidative stress and hypertension are the most common health problems for populations of developing countries, the study was focused on determination of antioxidant and anti-ACE activities in the product." (PMID 32093055, 2020). "The aim of this study was to assess the frequency of intraoperative hypotension in patients who had controlled hypertension on ACE inhibitor therapy." (PMID 32064194, 2020). "Hypertension is normally treated with drugs, in particular with angiotensin-converting enzyme (ACE) inhibitors." (PMID 32575679, 2020). "The modulation of RAS via ACE inhibition has been a primary strategy in the treatment of hypertension and heart failure." (PMID 32490731, 2020). "In the human and animal model of cardiovascular disease and hypertension, an increase in the ACE/AC2 ratio has been reported, as a consequence of an increased downregulation of ACE2 expression." (PMID 33117379, 2020). "ACE inhibitors not only treat hypertension but also decrease morbidity and mortality in heart failure patients and in patients with acute myocardial infarction." (PMID 32064194, 2020). "IF has also shown anti-hypertension effects via inhibiting the activity of angiotensin I converting enzyme (ACE)." (PMID 32349420, 2020). "Blood pressure and hypertension are immensely influenced by the Angiotensin I-converting enzyme (ACE), which acts through the renin angiotensin aldosterone system." (PMID 32443419, 2020).
Hypertension (continued). "In her previous medical documentation, we found that the patient had been treated for hypertension with a combination of an Angiotensin-converting enzyme (ACE) inhibitor and a diuretic." (PMID 32183010, 2020). "Intraoperative hypotension is more frequent in patients with controlled hypertension on ACE inhibitors although more studies need to be conducted on a larger population in order to determine a more definitive result." (PMID 32064194, 2020). "Angiotensin-converting enzyme (ACE) inhibitors are extensively prescribed to treat patients with hypertension, congestive heart failure, and diabetic nephropathy." (PMID 31984307, 2020). "Blood pressure: Hypertension and intake angiotensin converting enzyme (ACE) inhibitors and angiotensin receptor blockers (ARBs) increase risk of developing severe and fatal COVID-19." (PMID 32982999, 2020). "Three peptides (QLVP, QDVL, and QLDL), that can inhibit ACE activity and called ACE inhibitory peptides (ACEIPs), were extracted from G. lucidum and can be used to treat hypertension." (PMID 32317975, 2020). "ACE is responsible for the formation of angiotensin II, a powerful vasoconstrictor; excessive physiological levels of angiotensin II lead to hypertension." (PMID 32610462, 2020). "Clinical trials are ongoing, both to guide the use of ACE inhibitors for possible treatment of COVID-19 and for chronic management of patients with hypertension in the context of pandemic COVID-19." (PMID 32629804, 2020). "ACE catalyzes the conversion of angiotensin I into angiotensin II which acts as a vasoconstrictor leading to an elevated blood pressure; ACE inhibition therefore constitutes a major strategy to prevent hypertension." (PMID 33102467, 2020). "Damage in the kidneys from excessive ROS results in hypertension due to a malfunction in sodium reabsorption, upregulated ACE expression, and increased angiotensin II generation." (PMID 32325920, 2020). "Anti-hypertensive drug, enalapril, an inhibitor of the angiotensin converting enzyme (ACE), was also found to protect against ER stress-mediated hypertension caused by high methionine diet." (PMID 33053883, 2020). "With respect to hypertension, various compounds from seaweeds, such as protein-derived bioactive peptides and phlorotannins, can prevent hypertension by inhibition of angiotensin-I converting enzyme activity." (PMID 32102343, 2020). "Treatment of hypertension, which is much common in adults than in children, using ARBs or ACE inhibitors induces expression of ACE2, whose raised level led to the possible explanation to the worse effects of SARS-CoV-2 infection in adults." (PMID 33117174, 2020). "Hypertension is a common side effect of the novel antihormonal therapy (abiraterone acetate and enzalutamide) and is mainly managed using ACE inhibitors." (PMID 32412310, 2020). "ACE inhibitors and ARBs are the widely used medications in the treatment of arterial hypertension and in prevention of heart remodeling." (PMID 33162899, 2020). "The first example is that of the active pharmaceutical ingredient Lisinopril, an Angiotensin Converting Enzyme (ACE) inhibitor, widely used for hypertension and heart failure." (PMID 32824749, 2020). "Several drugs, such as beta-blockers, ACE inhibitors, angiotensin receptor blockers, calcium channel blockers, and aldosterone antagonists are prescribed to treat hypertension." (PMID 33171852, 2020). "Of all patients with pharmacologically treated hypertension, a minority were taking ACE inhibitor or ARB class agents and a majority were taking anti-hypertensive medications from alternate classes." (PMID 32702044, 2020). "This study is the first evidence confirming the ACE inhibitory activity of GANPs in addition to its antioxidant activity providing a promising treatment for hypertension disease." (PMID 33082415, 2020). "One study reported that the most preferred drug group in the treatment of hypertension is an ACE inhibitor." (PMID 33520303, 2020).
Hypertension (continued). "There is current debate concerning the use of angiotensin-converting enzyme (ACE) inhibitors or angiotensin II type 1 receptor blockers (ARBs), for hypertension management, during COVID-19 infection." (PMID 32685191, 2020). "The inhibition of human angiotensin I converting enzyme (ACE) has been regarded as a promising approach for the treatment of hypertension." (PMID 32178362, 2020). "On the other hand, a previous study reported that knee extension strength and walking speed was maintained in a patient with hypertension, upon treatment with an ACE inhibitor." (PMID 32334642, 2020). "Numerous studies, including large clinical trials, have demonstrated the greater value of tissue ACE inhibition vs. serum ACE inhibition in patients with hypertension, diabetes, renal disease, and heart failure." (PMID 32635289, 2020). "Enalaprilat is the active metabolite of prodrug enalapril, a widely used ACE inhibitor for the treatment of general hypertension and heart failure." (PMID 32547398, 2020). "Captopril suppressed high blood pressure and alleviated vascular changes and ACE activity in LHRs, similar to those of the SG extract (p < 0.05)." (PMID 33007813, 2020). "Some synthetic inhibitors of ACE activity (e.g., lisinopril, enaparil, or ramipril) are commonly used as drugs for treatment of cardiovascular diseases and high blood pressure." (PMID 32093055, 2020). "87.1% of all patients were taking ACE (angiotensin-converting enzyme) inhibitors or ARBs (angiotensin receptor blockers) to control high blood pressure." (PMID 32711448, 2020). "The ACE inhibitor, which is widely used as a therapeutic agent for hypertension, is reported to upregulate the ACE2 receptor expression." (PMID 33274196, 2020). "The ACE inhibitor is used as an initial therapy for high blood pressure in many situations (e.g., heart failure with reduced ejection fraction and chronic kidney disease)." (PMID 33274196, 2020). "In future, we will be able to use the knowledge of inhibitors’ pharmacological properties, including those of bioactive compounds such as allicin, to make effective therapeutic drugs based on ACE inhibition to cure hypertension." (PMID 30875817, 2019). "Because the production of angiotensin II increases blood pressure, the inhibition of ACE is a reliable strategy to control hypertension." (PMID 31336853, 2019). "Chronic treatment of hypertension and/or heart failure very often includes a renin-angiotensin system inhibitor (RASi, angiotensin-converting enzyme inhibitors [ACE-Is] or angiotensin receptor blockers [ARBs]." (PMID 30836981, 2019). "In melatonin-deficient hypertension, the classical RAS, defined as the angiotensin-converting enzyme (ACE)/angiotensin (Ang) II/angiotensin type 1 receptor (AT1R) axis, is activated." (PMID 31766163, 2019). "This evidence, along with the augmented expression of angiotensin converting enzyme (ACE) in animal models of hypertension, indicates that intrarenal RAS activation has a role in intratubular Ang II formation." (PMID 31680980, 2019). "This indicate that ovotransferrin have theoretic ACE inhibitory after human digestion tract, but still too soon to say that egg can regard as an anti-hypertension strategy food." (PMID 31758024, 2019). "The contribution of neurohormones in the progression of hypertension has led to new treatment modalities such as β-blockers and angiotensin-converting enzyme (ACE) inhibitors." (PMID 31048753, 2019). "In terms of hypertension control, one meta-analysis revealed that sex-specific outcome data were only reported in 43% of clinical trials reviewed, with ACE inhibitors and ARBs showing a small increase in cardiovascular benefit in men versus women." (PMID 31262355, 2019). "Despite the efforts for the management of hyperglycemia and hypertension using current therapies, such as angiotensin converting enzyme (ACE) inhibitors and angiotensin II receptor blockers (ARBs), the risk of DN progression has still not been reduced." (PMID 31212704, 2019).